TPD52 (tumor protein D52)
Synonyms: D52; hD52; N8L; PC-1; PrLZ
Tractability: PROTAC: ubiquitination databases record sites on it; its protein half-life has been measured.
Gene: Protein-coding gene on chromosome 8 (80,034,745 to 80,231,232, reverse strand). Ensembl gene ENSG00000076554.
Subcellular location (Human Protein Atlas): Cytosol; Golgi apparatus; Primary cilium
Pathways (Reactome):
Vesicle-mediated transport: Golgi Associated Vesicle Biogenesis
Gene Ontology:
Molecular function: calcium ion binding; protein binding; protein homodimerization activity; identical protein binding
Biological process: B cell differentiation; anatomical structure morphogenesis; positive regulation of cell population proliferation; secretion
Cellular component: cytoplasm; endoplasmic reticulum; perinuclear region of cytoplasm; glutamatergic synapse; synapse
Genetic constraint (gnomAD): Loss-of-function variants: 14 observed, 26.39 expected, observed/expected ratio (o/e) 0.53, 90% interval 0.35 to 0.83. The upper end of that interval is the gene's LOEUF score, 0.83, which puts it in group 3 of 6, group 1 being the genes least tolerant of losing a copy. Missense variants: 193 observed, 224.26 expected, observed/expected ratio (o/e) 0.86, 90% interval 0.76 to 0.97. Synonymous variants: 78 observed, 86.39 expected, observed/expected ratio (o/e) 0.9, 90% interval 0.75 to 1.09.
Homologues: Orthologues: macaque TPD52 (99% identical), dog TPD52 (96% identical), guinea pig TPD52 (91% identical), rat Tpd52 (90% identical), mouse Tpd52 (85% identical), pig TPD52 (84% identical), chimpanzee TPD52 (72% identical), tropical clawed frog tpd52 (63% identical), zebrafish tpd52 (49% identical), Drosophila melanogaster CG5174 (31% identical), Caenorhabditis elegans F13E6.1 (30% identical). Paralogues in human: TPD52L1 (54% identical), TPD52L2 (45% identical), TPD52L3 (27% identical).
Diseases named in the same sentence as TPD52 in open-access papers:
TPD52 is named in the same sentence as 74 diseases in open-access papers, as found by Europe PMC text mining. Sharing a sentence is not in itself a finding about the gene and the disease. The quoted sentences say what the papers report.
breast carcinoma (46 papers, 2005 to 2025). "For example, TPD52 was identified as a potential tumor-associated antigen in breast cancer through immunoscreening of a cDNA expression library derived from breast cancer tissues." (PMID 40973691, 2025). "By exploring TCGA‐BRCA cohort data, we also found that TPD52 expression is associated with clinical outcomes and metabolic gene expression in breast cancer patients." (PMID 35666017, 2023). "TPD52 is an oncogene and closely associated with prostate, breast cancer, and other cancers, which was consistent with our results." (PMID 36998462, 2023). "According to current research, TPD52 is known as a potential cancer-causing gene (oncogene) located on chromosome 8q21, formerly observed to be amplified and up-regulated in breast cancer." (PMID 34099820, 2021). "Overexpressed TPD52 has been identified as a potential driver gene that is highly associated with regeneration and poor prognosis of breast cancer." (PMID 31649118, 2019). "This is also consistent with reports of TPD52 being included in gene signatures associated with unfavourable prognosis, and with the clinical significance of chromosome 8q21 gain in breast cancer." (PMID 20846453, 2010). "As a potential driver gene, TPD52 is highly associated with regeneration in breast cancer." (PMID 31649118, 2019). "Another example is TPD52 which was highly associated to regeneration; this gene has previously been suggested as a potential driver gene and reported amplified and overexpressed in various cancer types, including breast cancer." (PMID 23382830, 2013). "Hence, the present study intends to find the expression pattern of KLF3, miR-124, TPD52, and PKCε in breast cancer patients which may serve as effective diagnostic biomarkers." (PMID 33490232, 2020). "Our findings identified that Star-PAP regulates TPD52 by modulating miR-449a/34a, which may be an important molecular mechanism underlying the tumorigenesis of breast cancer and provide a rational therapeutic target for breast cancer treatment." (PMID 31649118, 2019). "TPD52 was initially found to be highly expressed in human breast cancer, located at chromosome 8q21 —a region frequently amplified in tumors and closely associated with cell proliferation, apoptosis, and metastasis." (PMID 40973691, 2025). "Continued research into TPD52's mechanisms and applications will be essential for integrating this knowledge into clinical practice, ultimately improving outcomes for breast cancer patients." (PMID 39757112, 2025). "These aberrations highlighted well-known breast cancer-associated genes, such as MDM4, ZNF595, FGFR4, HIST1H1B, TPD52, DECR1, GRB7, and JUP55." (PMID 40162205, 2025). "TPD52 represents a promising target for therapeutic intervention and a valuable biomarker in breast cancer." (PMID 39757112, 2025). "Several studies identified the TPD52 gene sequence by its increased expression in human breast cancer tissue and in lung cancer cell lines." (PMID 39411371, 2024). "A previous study showed significant apoptosis following knockdown of TPD52 in the HER2-overexpressing human breast cancer cell line (SK-BR-3)." (PMID 39355533, 2024). "The NEAT1/miR-218-5p/TPD52 axis was shown to promote cell proliferation and migration of breast cancer cells." (PMID 37310654, 2023). "Upon binding to these HER2/Neu receptors, the exosomes transferred siRNA molecules to the breast cancer cells, downregulating the tumor protein D52 that was overexpressed by the breast cancer cells." (PMID 37047335, 2023). "The protein expression profiles from the Human Protein Atlas have revealed that TPD52 is upregulated in the majority of breast cancer tissues." (PMID 35666017, 2023). "When the miR-101-5p-associated pathways in breast cancer were assessed using RNA-seq, a particular group of genes, HMGB3, ESRP1, GINS1, TPD52, SRPK1, VANGL1, and MAGOHB, were suggested to be associated with a poor prognosis of BC." (PMID 38132441, 2023).
breast carcinoma (continued). "The target genes of miR-139-5p were predicted by using an online database TargetScan and miRDB, and three key genes, FBN2, MEX3A, and TPD52, were screened in combination with differentially expressed genes in different molecular subtypes of breast cancer." (PMID 35433464, 2022). "Expression of miR-124 and TPD52 were shown to be decreased and increased, respectively, in blood of breast cancer patients, a result that is in accordance with the findings of the current study." (PMID 35577881, 2022). "The TPD52 gene, first found in breast cancer, is in the core region of chromosome 8q21 amplification." (PMID 34565443, 2021). "Tumor protein D52 is up-regulated in prostate cancer, breast cancer, and also in ovarian cancer due to gene amplification." (PMID 34099820, 2021). "The focus of this study was to explore the influence of Krüppel-like factor 3 (KLF3), tumor protein D52 (TPD52), microRNA 124 (miR-124), and protein kinase C epsilon (PKCε) expression on breast cancer." (PMID 33490232, 2020). "Tumor protein D52 (Tpd52) was 6-fold upregulated, which is in consistence with reports showing high overexpression in many solid tumors and in particular breast cancer." (PMID 32793490, 2020). "So, in the current study, the association between the expressions of TPD52, KLF3, miR-124, and PKCε and clinicopathological attributes of breast cancer patients is also inferred." (PMID 33490232, 2020). "This can be presumed that radio-, chemo-, or combined therapy in breast cancer influences the expression of oncogene TPD52 which suggests that TPD52 can be a potential therapeutic target for the metastatic and luminal B group of breast cancers." (PMID 33490232, 2020). "Contrary to KLF3, in vitro results of the present study have shown the upregulated expression of TPD52 (2-fold) in breast cancer patients as compared to healthy controls." (PMID 33490232, 2020). "The RNA samples isolated from the blood of breast cancer patients were analyzed by qPCR for the expression of TPD52, KLF3, miR-124, and PKCε." (PMID 33490232, 2020). "Overexpression of TPD52 correlates with poor prognosis in breast cancer patients, and in cell models, TPD52 overexpression promotes proliferation and invasion." (PMID 31672706, 2020). "The breast cancer patients (n=1992) expressed significantly higher levels of TPD52 than the normal donors (n=144)." (PMID 31649118, 2019). "To explore the correlation between Star-PAP and TPD52 in human breast cancer cells, we first examined the expression of Star-PAP and TPD52 in a panel of breast cancer cell lines and two mammary epithelial cell lines." (PMID 31649118, 2019). "TPD52 is one member of the TPD52-like protein family, which was originally found upregulated in human breast carcinoma and further identified overexpressed in a variety of malignancies." (PMID 31649118, 2019). "Tumor-suppressive microRNA-449a and microRNA-34a (miR-449a/34a) were recently reported to inhibit breast cancer cell migration and invasion via targeting TPD52." (PMID 31649118, 2019). "We examined the effects of Brefeldin A (BFA), a fungal metabolite known to disrupt the Golgi structure, in TPD52-expressing 3T3 cells, and in human AU565 and HMC-1-8 breast cancer cells that endogenously express TPD52." (PMID 31278300, 2019). "Taken together, these data suggested that TPD52 was directly modulated by miR-449a and miR-34a in human breast cancer cell lines." (PMID 31649118, 2019). "Knockdown of TPD52 by miRNA mimic in breast cancer cells increased E-cadherin expression levels while decreasing TGF-β and N-cadherin levels." (PMID 31590453, 2019). "Recent studies showed that tumor-suppressive microRNA-449a and microRNA-34a (miR-449a/34a) inhibit breast cancer cell migration and invasion via targeting TPD52." (PMID 31649118, 2019). "In the present study, we found that TPD52 is generally upregulated in breast cancer cell lines, especially in MDA-MB-468, MCF-7 and SK-BR-3 cells." (PMID 31649118, 2019).
breast carcinoma (continued). "Due to the important roles of Star-PAP in regulating the expression of a global miRNAs and mRNAs, the present study aimed to explore the effects of Star-PAP on miR-449a/34a and TPD52 expression in breast cancer." (PMID 31649118, 2019). "The present study aimed to explore the regulative roles of Star-PAP in miR-449a/34a and TPD52 expression in breast cancer." (PMID 31649118, 2019). "Our studies identified that Star-PAP regulated TPD52 through modulating miR-449/34a, which plays a critical role in inhibiting the cell proliferation and inducing the apoptosis of breast cancer cells." (PMID 31649118, 2019). "MiR-449a/34a have been reported to inhibit breast cancer cell migration and invasion through targeting TPD52." (PMID 31649118, 2019). "Tumor protein D52-like proteins (TPD52) are small proteins that were first identified in breast cancer, are overexpressed in many other cancers, but remain poorly characterized." (PMID 29284484, 2017). "TPD52 gene expression was found to be inversely correlated to miR-145-5p expression in both lung and breast cancer data sets from the TCGA consortium." (PMID 26440147, 2015). "TPD52 (hD52) that has been shown to be in the peak of the 8q21 amplicon in breast cancer cell lines was also over-expressed in a number of cancers in this cluster." (PMID 16042759, 2005). "In addition, TPD52 is regulated by various microRNA (miRNA) species, such as miR-34a, miR-449, and miR-1323, which can inhibit the proliferation and metastasis of breast cancer cells by targeting TPD52, and is involved in tumor progression." (PMID 40973691, 2025). "TPD52, a member of tumor protein family D5211, was discovered in the research of breast cancer." (PMID 38544991, 2024). "Clinically, high TPD52 expression predicts poor survival of breast cancer patients." (PMID 35666017, 2023). "Finally, we assessed the clinical significance of TPD52 expression in breast cancer patients using bioinformatics techniques." (PMID 35666017, 2023). "In addition, the key target genes of miR-139-5p, FBN2, MEX3A, and TPD52 also provide potential targets for personalized treatment of different molecular subtypes of breast cancer." (PMID 35433464, 2022). "In contrast, in the present study, whether TPD52, a target gene of miR-139-5p, plays a role in the proliferation and metastasis of breast cancer cells needs to be further investigated." (PMID 35433464, 2022). "In addition, overexpression of TPD52 was reported by systematic analysis of a hypoxia-related prognostic signature for breast cancer." (PMID 34217360, 2021). "Consistently, we also found that TPD52 was significantly upregulated in breast cancer samples." (PMID 31649118, 2019). "In addition, the elevated TPD52 expression also indicated a lower relapse-free survival in the four major breast cancer subtypes (basal-like, HER2-enriched, luminal A and luminal B)." (PMID 31649118, 2019). "Furthermore, the proposed Star-PAP-miR-449a/34a-TPD52 axis is involved in proliferation and apoptosis of breast cancer cells." (PMID 31649118, 2019). "Considering the regulatory relationship between Star-PAP and TPD52, we hypothesized that the tumor suppressing effect of Star-PAP in breast cancer cells might be mediated by modulating TPD52 expression." (PMID 31649118, 2019). "In addition, repression of EMT and restrained breast cancer cell migration and invasion were observed following TPD52 targeting by miR-34a." (PMID 31590453, 2019). "To clarify whether the effects of BFA on TPD52 protein redistribution were limited to stably-transfected 3T3 cells, we examined the breast carcinoma cell lines AU565 and HMC-1-849." (PMID 31278300, 2019). "Furthermore, Star-PAP-miR-449a/34a-TPD52 axis is involved in proliferation and apoptosis of breast cancer cells." (PMID 31649118, 2019). "Herein, we found that miR-449a and miR-34a could inhibit cell proliferation of breast cancer cells through suppressing TPD52." (PMID 31649118, 2019).
breast carcinoma (continued). "It was indicated that TPD52 expression in ovarian cancer tissue was higher compared with normal ovarian epithelium, and TPD52 was found to be overexpressed in prostate cancer and breast cancer." (PMID 28562687, 2017). "TPD52, upregulated nearly 2-fold in tumors of poor prognosis patients, has been shown to be overexpressed in colorectal cancer and ovarian cancer, and genomic amplification of TPD52 has been seen in prostate cancer and breast cancer." (PMID 24634783, 2014). "However, the finding that TPD52 is a favourable prognostic indicator in ovarian carcinoma patients contrasts with findings obtained in breast cancer." (PMID 20846453, 2010). "Notably, TPD52 is a survival factor for breast cancer cells that ERBB2 has increased." (PMID 39757112, 2025). "Consequently, exosomes carrying siRNA-TPD52 could target Her 2 positive breast cancer cells and obviously suppress oncogene TPD52 expression." (PMID 35155421, 2022). "These HER2 DARPin-Exo were subsequently loaded with TPD52 siRNA via electroporation, achieving up to 70% downregulation of TPD52 expression in HER2-positive breast cancer cells." (PMID 39204374, 2024). "Their expression and prognosis in the four types of breast cancer were observed separately, and the results showed that FBN2, MEX3A, and TPD52 were more expressed in luminal A, HER2, and TPD52 than in normal samples." (PMID 35433464, 2022). "The results showed that FBN2, MEX3A, and TPD52 were highly expressed in luminal A, luminal B, HER2-enriched, and basal-like breast cancers compared with normal samples." (PMID 35433464, 2022). "A total of three key genes were obtained after overlapping the predicted target genes with the differentially upregulated genes in the four types of breast cancer: FBN2, MEX3A, and TPD52." (PMID 35433464, 2022). "Human bone marrow mesenchymal stem cell-derived exosomes inhibited the growth of breast cancer cells and promoted the expression of FBN2, MEX3A, and TPD52 by transporting miR-139-5p." (PMID 35433464, 2022). "We identified 4 mRNAs (TPD52, BTG2, CCND2, LIFR) involved in the prognosis of breast cancer using survival analysis." (PMID 34545330, 2021). "Expression level of TPD52 was found to be elevated while KLF3, miR-124, and PKCε genes were downregulated in breast cancer patients in comparison to controls." (PMID 33490232, 2020). "So, the goal of the current study is to analyze the expression pattern of TPD52, KLF3, miR-124, and PKCε in breast cancer patients as well as to predict their possible correlation with clinicopathological characteristics of breast cancer." (PMID 33490232, 2020). "The fold change observed in samples has spotted the upregulation of TPD52 and downregulation of KLF3, miR-124, and PKCε in breast cancer." (PMID 33490232, 2020). "Compared with the mammary epithelial cells, the breast cancer cell lines expressed lower levels of Star-PAP mRNA and higher levels of TPD52 mRNA, as quantified by qPCR." (PMID 31649118, 2019). "The 2 breast cancer cell lines also showed significantly increased LD sizes 5 h post-BFA treatment, which was accompanied by significantly increased detection of TPD52 at LDs." (PMID 31278300, 2019). "In this study, we examined the effects of BFA upon the sub-cellular localisation and LD recruitment of TPD52 and other LD regulators in TPD52-expressing 3T3 cells, and in human AU565 and HMC-1-8 breast cancer cells, all of which contain prominent LDs." (PMID 31278300, 2019). "Besides the influence of well-known molecular aberrations in breast cancer such as BRCA1, BRCA2, HER2, and Ras, other genes such as S100A4, TPD52, and CDKs have been identified." (PMID 39355533, 2024). "TPD52 is known to be commonly overexpressed in breast cancer, but the physiological functions are not clear." (PMID 35666017, 2023). "Tumor Protein D52, TPD52 in short, enables the progression of breast cancer." (PMID 37564195, 2023).
breast carcinoma (continued). "The results indicated high expression of TPD52 (p = 0.0017) and low expression of KLF3 (p = 0.0048), miR-124 (p = 0.0048), and PKCε (p = 0.0043) in blood of breast cancer patients as compared to healthy controls." (PMID 33490232, 2020). "The expression of TPD52, KLF3, miR-124, and PKCε in breast cancer patients was measured." (PMID 33490232, 2020). "While high TPD52 expression in breast cancer has been reported to be an adverse prognostic factor, the clinical significance of increased TPD52 expression in ovarian cancer has not been directly investigated." (PMID 20846453, 2010). "Breast cancer cells may be inhibited from autophagy, proliferation, and migration by HMGB1; in addition, several research studies have discovered that miR-107 controls PTX sensitivity via Wnt/-catenin signaling pathway, which targets TPD52." (PMID 36816358, 2023). "Likewise, enhanced TPD52 expression and lower KLF3 expression in the metastatic group of patients in comparison to the control and nonmetastatic group can be considerably utilized for diagnosis purpose of breast cancer at the molecular level." (PMID 33490232, 2020). "Inspired by that, TPD52 is a well-known oncogene overexpressed in breast cancer, we sought to determine whether regulation between Star-PAP and TPD52 was also involved in breast cancer development besides BIK." (PMID 31649118, 2019). "Given that TPD52 is closely associated with tumor progression, our study here identified a clearly regulatory relationship that Star-PAP regulates the expression of TPD52 via modulating miR-449a/34a, rather than the direct 3′-end processing way in breast cancer cells." (PMID 31649118, 2019). "We observed a negative correlation between the expression of TPD52 and Star-PAP in breast cancer." (PMID 31649118, 2019). "Moreover, the correlation analysis of the clinical data (264 breast cancer patients) from R2 database showed that there was a negative correlation between Star-PAP and TPD52 mRNA (r=−0.2036, Y=−0.1398*X+6.684, P=0.0009)." (PMID 31649118, 2019).